IFIT2 (interferon induced protein with tetratricopeptide repeats 2)
Diseases named in the same sentence as IFIT2 in open-access papers (continued):
Sharing a sentence is not in itself a finding about the gene and the disease.
infection (continued). "To verify that C6 and K7 impaired IFN-β, TNF-α, MIP-1α and IFN-β-dependent gene expression in innate immune cells, we infected human moDCs with 1 PFU/cell of MVA-WT, MVA-B, MVA-B ΔC6L and MVA-B ΔC6L/K7R and measured IFN-β, TNF-α, MIP-1α, IFIT1 and IFIT2 mRNA levels 6 h post-infection." (PMID 23826170, 2013). "Our study showed that the IFIT2 protein was up-regulated following infection with T1L, which may indicate that IFIT2 RNA expression is also induced after T1L infection." (PMID 23240068, 2012). "In these cells, IFIT2 pre-mRNA could be detected only following infection, and was present in significantly greater quantities in the absence of the E1B 55 kDa protein." (PMID 22912576, 2012). "IFIT2 RNA expression is induced following infection with MRV strain T3D." (PMID 23240068, 2012). "To find out whether a decrease of virus load observed in the presence of Iristatin results in a decrease of IFN or ISGs, we measured gene expression of IFN-β and four interferon-stimulated genes, namely ISG15, CXCL-10, OASL2, and IFIT2 in skin tissue two and 5 days after Hypr infection." (PMID 39821815, 2025). "The results demonstrated that both the mRNA and protein levels of IFIT1 and IFIT2 were increased in rIBV-ΔPL1pro-N infected cells at 16 and 20 h post-infection to different degrees, indicating that the N-terminal region of PL1pro affects the expressions of ISGs during later stages of infection." (PMID 38087313, 2023). "In addition, we performed the RNA velocity analysis on an embedding of the Calu-3 cells calculated without viral genes, which is now driven by the genes induced by the infection such as IFIT2 or ARRDC3, leading to a convergence of highly infected cells independent of the virus." (PMID 33585804, 2021). "Here, we report on the antiviral properties of the newly generated Ifit2−/− mice; these mice, but not Ifit1−/− mice, were highly susceptible to neuropathogenesis after intranasal infection with vesicular stomatitis virus (VSV), a negative sense, single-stranded RNA rhabdovirus." (PMID 22615570, 2012). "Among others, 2’-5’ oligoadenylate synthetase-like (OASL), Interferon induced protein with tetratricopeptide repeats 2, 3 and 5 (IFIT2, IFIT3, IFIT5) were up-regulated in female-derived macrophages upon infection." (PMID 40794782, 2025). "Differential gene expression analysis in hROs at 24 h post-infection revealed a robust upregulation of antiviral genes (e.g. IFIT1, IFIT2, MX1, and OAS2) and pathways related to antiviral innate immunity and viral replication in rRVFV versus mock comparisons." (PMID 41255708, 2025). "The host innate immune and inflammatory responses to infection were assessed by measuring changes in mRNA expression of a chemokine, CCL5, and an interferon-stimulated gene (ISG) IFIT2, using cell lysates harvested at 24 hpi." (PMID 40295862, 2025). "IFIT2 binds to and enhances translation of IAV transcripts during infection to increase viral protein production and, ultimately, viral replication." (PMID 40497724, 2025). "Following infection of PAMs with ASFV-WT and ASFVΔMGF360–4L, IFIT2, IFIT3, and IFIT5 transcription were significantly up-regulated." (PMID 41153955, 2025). "In contrast to the footpad infection model, when mice were infected intranasally with VSV, Ifit2 expression in neuronal cells was essential to prevent death and neurological diseases." (PMID 38888342, 2024). "Despite BA.4 and BA.5 replicating similarly to BA.2 in HAEs, we consistently observed reduced innate activation, measured by ISG induction, after BA.4 and BA.5 infection (IFNB, CXCL10, IFIT1, IFIT2, DDX58 and RSAD2)." (PMID 38228858, 2024). "IFIT1, IFIT2 and ICP27 proteins were upregulated and, consistent with previous results, citrullinated following infection with HSV-1, especially at 16 hpi." (PMID 38055760, 2023). "ISGs IFIT2 and IFIT3 were strongly expressed in both lineage infections as verified using Western blotting." (PMID 37766362, 2023).
infection (continued). "Indeed, several key antiviral effectors and inflammatory drivers remained upregulated at late infection time points in older mice when compared to the 10 w-old animals, including several that were poorly upregulated initially in the older cohort; these included Il6, Isg15, Cxcl10, and Ifit2." (PMID 36679892, 2022). "The cluster three gene IFIT2, an ISG, was greatly induced at 4 hpi and gradually decreased as infection progressed." (PMID 35458509, 2022). "The previous research reported that IFIT1, IFIT2, IFTI3, IFIT3, IFI44, HERC4, and OASL genes are antitumoral effects and modulated the inflammatory response in cancer and infection." (PMID 35941292, 2022). "ISGs and immune response genes such as IFIT1, IFIT2, IFIH1, MX1, MX2, and RSAD2 were highly down-regulated in response to all viruses at later time points of infection, confirming our transcriptome data." (PMID 33791243, 2021). "(F) RT-PCR analysis of IFNB1, IFIT2, IFIT1, TNF, IL6, and CCL20 mRNA levels in HEK293T cells transfected with HA-Ev or HA-RTN3 followed by infection with VSV-eGFP (MOI = 1) at the indicated timepoints." (PMID 34313226, 2021). "p62 knockdown significantly reduced levels of IRF7, ISG15, IFIT1, IFIT2, and IFIT3 genes, suggesting that p62 was required for maximal activation of the innate immune response during KSHV primary infection." (PMID 33414399, 2021). "Further RT-PCR analyses determined that the levels of IFNB1, IFIT2, IFIT1, TNF and the proinflammatory cytokines CCL20 and IL6 were enhanced by RTN3 knockdown during VSV infection, while the amplification of VSV was compromised." (PMID 34313226, 2021). "Clear kinetics of this response were observed during infection with MA08, starting with the production of ISGs, IFIT2 and MX2 at 48 hpi." (PMID 34671358, 2021). "We found that the expression levels of IRF-7, IFIT1, IFIT2, and RIG-I showed statistically significant differences after infection with hNS1-expressing recombinant viruses or aNS1-expressing recombinant viruses at certain time points." (PMID 31597767, 2019). "We provide evidence that IFIT2 increases the pathological effects of invasive C. albicans and that administration of IFN-β has deleterious effects during infection." (PMID 29666281, 2018). "Both classical monocytes and NK cells upregulated the ISGs IFIT2 and IFIT3 early in infection and ATAC-seq peaks were identified at sites containing ISRE motifs." (PMID 30596671, 2018). "The expression levels of some ISGs (IFIT1, IFIT2, IFIT3) and proinflammatory cytokines (IL-6, IL-8) in DDX1-knockdown cells were analyzed after TGEV infection." (PMID 28848548, 2017). "Four ISGs, IFIT1, IFIT2, IFNβ, and OASL1, were analyzed following infection in the presence of DMSO or KPT-185." (PMID 27902702, 2016). "Infection of primary monocytes with PDK53 at both 1 and 10 MOI resulted in greater levels of CXCL10, ISG20 and IFIT2 mRNA levels compared to 10 MOI of 16681." (PMID 27185466, 2016). "Most of the ISGs and cytokines, including IFNβ, IFIT2, TNFα, and IL6 were detected two hours post-infection." (PMID 25728279, 2015). "IFIT-2 mRNA, which has been previously defined as an ISG to restrict VSV replication in the brain, was induced only at day 6 post infection." (PMID 24675692, 2014). "Pre-mRNAs transcribed from the IL6, IFIT2 and STAT1 genes were present in mock-infected cells, and decreased significantly in concentration following infection with AdEasyE1, whereas only minimal differences in GAPDH mRNA were detected." (PMID 22912576, 2012). "The results showed that SVA infection could significantly downregulate the expression of IFNB, IFIT2, IFIT1 and OAS1 induced by poly (I:C), but this inhibitory effect was weakened in VP2 knockdown cells." (PMID 41319264, 2026). "Of the clusters that increased during infection, cluster 3 contained subsets of type I IFN-inducible and inflammatory myeloid-related genes that were only modestly reduced by anti-IFNAR treatment, including Acod1, Ifit2, and Retnla." (PMID 40986319, 2025).
infection (continued). "In addition, expression of the protein-coding genes CXCL10, IFIT1, NCOA7, IFIT2, SIX3, and RPSA was increased during infection." (PMID 40510596, 2025). "However, expression of the IFN-stimulated gene (ISG) IFIT2 was only slightly increased (less than 2-fold upregulation), while ISG15 levels were even downregulated during infection after p62-knockdown." (PMID 40247289, 2025). "Finally, at 72 hours post-PIV3 infection, the transcriptional response remains interferon-centric, with continued expression of IFIT1, IFIT2, IFIT3, MX1, and OAS2." (PMID 39591472, 2024). "The idea that viruses may utilize IFN responses to promote infection has recently been demonstrated for influenza virus, whereby the virus utilizes the host ISG IFIT2 to enhance the translational efficiency of viral RNAs." (PMID 39253971, 2024). "Expression of luciferase, as well as endogenous IFIT-2 and CXCL-10 was significantly reduced following ruxolitinib treatment of Gag-LUC-infected cells indicating that infection with this Gag-LUC fusion virus induces type I IFN production, to induce endogenous ISG and IFN reporter expression." (PMID 38778414, 2024). "Likewise, the 3’ UTRs of Ddx58, Ddx3x, Ddx21, Ifit2 and Ifit3, were significantly shorter in primary BMDMs from Cpsf6+/- mice, and such shortening was more pronounced upon VSV-eGFP infection." (PMID 38416782, 2024). "Together, this demonstrated that the early secretion of mucosal IFN-α in non-immune horses promotes the upregulation of interferon-stimulated genes, including IFIT2 and IFIT3, while activation of this pathway seems unnecessary for EHV-1 immune horses to control and clear infection." (PMID 39162558, 2024). "Expression profiles of genes, IFIT2 and IFIT3, were similar throughout the infection." (PMID 39162558, 2024). "As in THP-1 cells, infection of MDM with Gag-LUC induced a robust type I IFN response leading to significantly higher expression of CXCL-10, IFIT-2 and MxA, as well as CXCL-10 protein compared to VSV-G pseudotyped LAI infection, all of which was reduced by ruxolitinib treatment." (PMID 38778414, 2024). "Early acute infection and A549 infected cells shared 150 upregulated genes including ATF3, a stress induced transcription factor, as well as other genes involved in the innate immune response such as MX1, DDX58/RIG-I, IFIT1, IFIT2, DHX58/MDA5, and OASL." (PMID 39065267, 2024). "Similarly, IFIT2-/- mice have increased viral replication in vivo during vesicular stomatitis virus, WNV, and mouse hepatitis virus (strain A59) infection (60, 62, –, 64)." (PMID 39162558, 2024). "Finally, at 72 hours post-PIV3 infection, the transcriptional response remains robust and interferon-centric, with continued expression of IFIT1, IFIT2, IFIT3, MX1, and OAS2." (PMID 39591472, 2024). "However, amounts of IFIT2 and IFIT3 appear to be slightly higher in B/Yamagata infections with an exceptionally strong band in B/Baltimore/R0337/2018 infection." (PMID 37766362, 2023). "Notably, multiple antiviral proteins were also dramatically decreased in PAMs during the PRRSV-ADE infection, including ISG15, ISG20, IFIT1 (ISG56), IFIT2 (ISG54), IFIT3 (ISG60), IFIT5 (ISG58), OAS1, Mx1, RSAD2, TRIM22, TRIM25 and TRIM34, except for TRIM52." (PMID 36680075, 2022). "We observed a temporal increase in expression of the Type I IFN response genes Il1rn, Ifit2, Ifit1 and Ifih1 (data not shown) upon infection." (PMID 34603294, 2021). "Some of the genes that were similarly modulated by MR766 and Rio-U1 related to cytokine signaling (CXCL10/11, CCL8) and the IFN response (IFIT2, ISG15, OAS2, DDX58, among others), suggesting some degree of similarity in signaling patterns following infection with either virus." (PMID 33405202, 2021). "In summary, Ifit2 plays a role in maintaining CX3CR1 surface expression in both CD45hi CD11b+ monocyte derived macrophages and CD45lo/int CD11b+ CNS resident microglia following MHV-RSA59 infection." (PMID 33253295, 2020).
infection (continued). "IFIT2 knockdown affected K-bZIP expression only during KSHV de novo infection and silencing of IFIT3 increased K-bZIP expression only during lytic reactivation." (PMID 31059555, 2019). "Interestingly, ISGs, including IFIT2, CXCL10, RIGI, and Mx1, were also detected very early after infection (4 to 12 hpi)." (PMID 31375585, 2019). "These nPro/HFs and V/HFs were recently utilized, alongside IRF3 KO CRISPR/Cas9 HFs, to demonstrate that expression of viperin, ISG15, IFIT1, IFIT2, IFIT3, Mx1, and Mx2 mRNA during infection with HCMV can be induced in an IRF3-dependent, STAT1-independent manner." (PMID 31921100, 2019). "The only gene up regulated in NH1067B-infected MDM that was not upregulated in NH1125B-infected MDM at 4.0 hours post infection was IFIT2." (PMID 28877226, 2017). "Along with IFIT2, IFIT1 and IFIT3 were also increased following infection with both strains." (PMID 29085037, 2017). "Four of these genes also showed >1.5 fold up-regulation in H5N1- compared with H1N1-infected cells at 3 h post-infection: TNF, IFN-induced protein with tetratricopeptide repeats 2 (IFIT2), macrophage inflammatory protein 1-β (CCL4L1), and phorbol-12-myristate-13-acetate-induced protein 1 (PMAIP1)." (PMID 20011590, 2009). "Similarly, almost 100% of CMV-Cre Ifit2 fl/fl and Nes-Cre Ifit2 fl/− mice exhibited various neuropathic symptoms after infection, whereas only approximately 40% of Ifit2 fl/fl mice, without Cre, displayed such symptoms." (PMID 38888342, 2024). "Infection of PMA‐treated THP‐1 shSAMHD1 cells with HIV‐1 GFP that had been produced in the presence of increasing doses of LPV led to a virus and LPV dose‐dependent increase in the expression of ISGs CXCL‐10, IFIT‐2 and MxA at the mRNA level, and CXCL‐10 protein secretion." (PMID 32852081, 2020). "Moreover, Ifit2 failed to protect mice from another neurotropic virus, encephalomyocarditis virus, nor was it necessary for protecting organs other than brain from infection by VSV." (PMID 22615570, 2012). "As with VSV, neither IFIT2 nor IFIT3 alone exerted an antiviral effect on PIV3, but their co-expression significantly inhibited infection." (PMID 41093992, 2025). "Specifically, suppression of IFI6 and OAS1 was impaired by HAdV-B7 when RuvBL2 was knocked down, but not of IFIT1 nor IFIT2, while only OAS1 expression in HAdV-B14 infection was affected by RuvBL2 knockdown." (PMID 38940561, 2024). "Similar to the lab-adapted strains, we observed six ISG-related DAPs (IFIT1, IFIT2, IFIT3, OAS3, ISG15, and MX1) significantly upregulated compared to MOCK infected UNOs, upon infection with clinical isolates of PeV-A3, but not PeV-A1." (PMID 38514653, 2024). "Unlike IFIT1 and IFIT2, IFIT3 showed only a slight increase in citrullination during infection, which was not statistically significant (p = 0.06)." (PMID 38055760, 2023). "HIV-Luc IND116A infection of siNT control cells resulted in low but significant induction of ISG15, IFIT1, and IFIT2 compared to that in noninfected control cells." (PMID 37922361, 2023). "Expression of eight of these genes (IFIH1, OAS2, IFIT1, IFIT2, IFIT3, IFIT5, USP18 and DDX58F) was significantly elevated in response to VSV-ΔM51 infection in permissive cells, but not in resistant PDACs." (PMID 27533247, 2016). "Neither CMV-Cre Ifit2 fl/fl mice nor Nes-Cre Ifit2 fl/− mice survived beyond 6 days after intranasal infection with a low dose [400 plaque-forming units (pfu)] of VSV, whereas 60% of Ifit2 fl/fl mice, without Cre, survived beyond 14 days post infection." (PMID 38888342, 2024). "Interestingly, the expression of MX2, IFIT2, OASL and OAS2 was up-regulated after infection with HEV-3f in both pig livers and HepaRG cells but not in pig livers infected with HEV-3c." (PMID 38058490, 2023).
infection (continued). "Results showing that IFIT1, IFIT2, and IFIT3, but not IFIT5, were induced with similar kinetics by DV infection suggest the possibility of co-regulation, and also the coordination and non-redundant functioning of these molecules in IFN-mediated signaling events, as observed in neurons." (PMID 24223959, 2013). "However, IFIT2, IFIT3, and IFN-α were not increased in immune horses at any time after infection." (PMID 39162558, 2024). "However, the infection of PKR−/− mice did not impair Ifnα/β, Ifit1, or Ifit2 mRNA upregulation." (PMID 38140641, 2023).